SREK1 (splicing regulatory glutamic acid and lysine rich protein 1)
Description:
Participates in the regulation of alternative splicing by modulating the activity of other splice facors. Inhibits the splicing activity of SFRS1, SFRS2 and SFRS6. Augments the splicing activity of SFRS3 (By similarity).
Synonyms: SRrp86; SRrp508; SFRS12; DKFZp564B176
Tractability: PROTAC: UniProt records ubiquitination sites on it; ubiquitination databases record sites on it; its protein half-life has been measured.
Gene: Protein-coding gene on chromosome 5 (66,139,971 to 66,183,615, forward strand). Ensembl gene ENSG00000153914.
Subcellular location: Nucleus
Subcellular location (Human Protein Atlas): Nuclear speckles; Nucleoplasm
Gene Ontology:
Molecular function: protein binding; RNA binding; nucleic acid binding
Cellular component: nuclear speck; nucleoplasm; nucleus
Genetic constraint (gnomAD): Loss-of-function variants: 11 observed, 59.65 expected, observed/expected ratio (o/e) 0.18, 90% interval 0.12 to 0.31. The upper end of that interval is the gene's LOEUF score, 0.31, which puts it in group 1 of 6, group 1 being the genes least tolerant of losing a copy. Missense variants: 594 observed, 760 expected, observed/expected ratio (o/e) 0.78, 90% interval 0.73 to 0.84. Synonymous variants: 258 observed, 260.82 expected, observed/expected ratio (o/e) 0.99, 90% interval 0.89 to 1.1.
Homologues: Orthologues: chimpanzee SREK1 (99% identical), pig SREK1 (97% identical), dog SREK1 (97% identical), macaque SREK1 (94% identical), rabbit SREK1 (93% identical), guinea pig SREK1 (84% identical), tropical clawed frog srek1 (59% identical), zebrafish srek1 (51% identical), Drosophila melanogaster Srp54 (29% identical). Paralogues in human: SRSF11 (38% identical).
Diseases named in the same sentence as SREK1 in open-access papers:
SREK1 is named in the same sentence as 14 diseases in open-access papers, as found by Europe PMC text mining. Sharing a sentence is not in itself a finding about the gene and the disease. The quoted sentences say what the papers report.
hepatocellular carcinoma (3 papers, 2022 to 2025). A malignant tumor that arises from hepatocytes. "In addition, isoform switching of SREK1 has been implicated in hepatocellular carcinoma progression through the modulation of nonsense-mediated decay and competing endogenous RNA networks." (PMID 41208460, 2025). "1C8 also affects SRSF10-dependent SREK1 alternative splicing in a hepatocellular carcinoma cell line, and inhibits the growth of Hep3B cells." (PMID 38753413, 2024). "1C8 reprograms the SRSF10-dependent alternative splicing of BCLAF1 and SREK1 in colorectal and hepatocellular carcinoma cell lines, respectively." (PMID 38753413, 2024).
Obesity (2 papers, 2025). Accumulation of substantial excess body fat. "Recent studies have linked SREK1 dysfunction to metabolic disorders, including obesity, type 2 diabetes, and hepatic steatosis." (PMID 41208460, 2025). "In conclusion, we discuss here a previously unreported cause of syndromic obesity, that of biallelic SREK1 mutations in RRMs that impair SNORD115/116 RNA expression and mimic aspects of PWS via a splicing-driven mechanism." (PMID 40549565, 2025). "Biallelic variations in SREK1 reduce SNORD115/116 expression, linking severe obesity and Prader-Willi-like traits, offering genetic and molecular insights into a new form of syndromic obesity." (PMID 40549565, 2025).
diabetes (1 paper, 2025). "Collectively, these findings support the notion that SREK1 serves as a molecular link between transcriptomic dysregulation and metabolic disease, including diabetes-related complications." (PMID 41208460, 2025). "Although these findings have primarily been linked to neurodevelopmental phenotypes, concurrent metabolic abnormalities—such as insulin resistance and impaired energy homeostasis—suggest that SREK1 may also influence hypothalamic and endocrine pathways relevant to diabetes." (PMID 41208460, 2025). "Notably, SREK1 and GLIPR1 were commonly detected across all four tissues, suggesting potential systemic regulators of diabetes-related complications." (PMID 41208460, 2025).
lung carcinoma (1 paper, 2022). "Out of 12 hub genes, only 4 (IRAK2, SREK1, C1QTNF2 and DDX3Y) have shown significant gene expression in lung cancer compared to the normal tissues." (PMID 36194576, 2022). "Additional COPD hub genes like SREK1, TMEM67, CDC42BPA, DPF3, and ASB4 were identified as prognostic markers in lung cancer, which is reported in 1% of COPD patients." (PMID 36194576, 2022). "Medium staining detection of CDC42BPA and IRAK2 were found in both normal and cancer lung tissue in addition to SREK1 and C1QTNF2 which was observed in medium in normal tissue but higher in lung cancer tissue." (PMID 36194576, 2022). "Interestingly, we have also identified that the expression status of other COPD hub genes like SREK1, TMEM67, CDC42BPA, DPF3, and ASB4 improves the survival duration of lung cancer patients, hence they may act as potential molecular drug targets and/or biomarkers for both COPD and/or lung cancer." (PMID 36194576, 2022).
cancer (3 papers, 2016 to 2022). A tumor composed of atypical neoplastic, often pleomorphic cells that invade other tissues. "Furthermore, two genes involved in splicing (SREK1 and SNRPD1) had some of the most differentially spliced A3SS events, consistent with the importance of autoregulated splicing networks in cancer." (PMID 34440489, 2021).
tumor (2 papers, 2021 to 2022). "As more SREK1L was detected in HCC tumor than in HCC-MN tissues, we detected SREK1 expression in slides of HCC-MN tissues using an antibody recognizing both forms." (PMID 35296659, 2022). "The use of the proximal 3′ss in SREK1 leads to a premature terminating codon (PTC), which would most likely mean an unstable transcript or protein and decreased SREK1 activity in the tumor would be predicted." (PMID 34440489, 2021).
SREK1 also shares sentences with these, for which no sentence is quoted: infection (2 papers); asthma (1); colon adenocarcinoma (1); Hepatic steatosis (1); Insulin resistance (1); lung disease (1); metabolic disorders (1); type 2 diabetes (1).